PHF5A (PHD finger protein 5A)
Diseases named in the same sentence as PHF5A in open-access papers (continued):
Sharing a sentence is not in itself a finding about the gene and the disease.
cancer (continued). "The findings suggested that the body may regulate the active expression of PHF5A by controlling its methylation levels, and DNA methylation played a role in the action of PHF5A in cancers." (PMID 37845358, 2023). "Consequently, conducting a comprehensive analysis of molecular mechanisms and regulatory functions of PHF5A across various types of cancer is crucial in order to offer new insights and approaches for cancer treatment." (PMID 37845358, 2023). "Patients with various cancer types were evaluated for their PHF5A expression and prognosis." (PMID 37845358, 2023). "Thus, we can conclude that PHF5A expression varies across molecular and immune subtypes in different kinds of cancer." (PMID 37845358, 2023). "In addition, we noticed that the higher PHF5A expression in these cancers basically corresponded to the higher stage or grade of cancer." (PMID 37845358, 2023). "Additionally, the analysis of the correlation between methylation of PHF5A promoter and prognosis has been firstly conducted, and we found that promoter methylation of PHF5A played a guiding role in prognosis in some cancers." (PMID 37845358, 2023). "Furthermore, we determined the association of PHF5A expression with chemokine receptors, chemokines and MHC genes in pan-cancer." (PMID 37845358, 2023). "Thus, it was proposed that PHF5A participated in alternative splicing and played a critical role in cancer development." (PMID 37434235, 2023). "Notably, a close correlation was found between PHF5A expression and all types of cancer, except for CHOL and UCS." (PMID 37845358, 2023). "However, knowledge of the splicing function of PHF5A is still limited, and the role of PHF5A in cancer is rarely investigated." (PMID 30932358, 2019). "Moreover, PHF5A was demonstrated to be a prognostic biomarker by pan-cancer analysis." (PMID 39030507, 2024). "Moreover, molecular subtypes showed differential expression of PHF5A in the majority of cancers." (PMID 37845358, 2023). "Further, PHF5A knockdown or silencing coupled with concomitant administration of conventional chemotherapeutic agent might also be a suitable site specific/targeted therapeutic option for cancer therapy." (PMID 37483794, 2023). "However, the correlation of immune cells with PHF5A expression might vary in various cancers, indicating that PHF5A might have distinct immunomodulatory functions in different cancers." (PMID 37845358, 2023). "Thus, it was proposed that the PHF5A protein could play a general role in both basic and essential cellular functions, including cancer development." (PMID 29566713, 2018). "In oncogenesis, PHD finger proteins like PHF1, PHF5A, and PHF8 contribute to cancer progression by dysregulating chromatin." (PMID 38813086, 2024). "SF3B1 and SF3B7 (also known as PHD finger protein 5A, PHF5A) have been extensively investigated for their functional roles in multiple cancers, including CRC." (PMID 38671459, 2024). "In almost all cancers detected, T cell CD4+ Th2 and common lymphoid progenitor were positively correlated with PHF5A expression, while T cell CD4+ central memory was negatively correlated with it." (PMID 37845358, 2023). "PHF5A is an essential splicing factors belonging to SF3B complex that presents pivotal involvement in alternative splicing regulation and cancer progression." (PMID 37483794, 2023). "Assessment of PHF5A function enrichment was performed with IPA bioinformatics tools; the two classifications of “Cancer” and “Cell cycle” were significant." (PMID 29566713, 2018). "Most importantly, prior research has primarily examined the role of PHF5A in specific cancers, with no comprehensive research exploring survival significance or biological role of PHF5A across cancers." (PMID 39030507, 2024). "PHD-finger domain protein 5 A (PHF5A) has been reported to participate in various cancers; however, there has been no pan-cancer analysis of PHF5A." (PMID 39030507, 2024).
cancer (continued). "However aberrant/dysregulated splicing occurring from the snooping of different spliceosomal factors/co-factors may provoke cancer progression and propagation attributed to the formation of abnormal protein isoform responsible for over expression of different splicing modulators such as PHF5A." (PMID 37483794, 2023). "Further, the participation of PHF5A in regulating the growth of cancer stem cells might not be ignored." (PMID 37483794, 2023).
infection (1 paper, 2016). The state of being infected such as from the introduction of a foreign agent such as serum, vaccine, antigenic substance or organism. "Furthermore, two of the proteins, PHF5A and SF3B1, were coimmunoprecipitated with AAV capsids after infection." (PMID 27252527, 2016).
PHF5A also shares sentences with these, for which no sentence is quoted: endometrial cancer (4 papers); colon adenocarcinoma (2); head and neck squamous cell carcinoma (2); rectal adenocarcinoma (2); skin cancer (2); basal cell carcinoma (1); benign tumors (1); Bladder urothelial carcinoma (1); breast tumors (1); cancer of female genital organs (1); cancer of male genital organs (1); cervical squamous cell carcinoma (1); cholangiocarcinoma (1); colon cancer (1); colorectal tumors (1); diffuse large B-cell lymphoma (1); endocervical adenocarcinoma (1); esophageal squamous cell carcinoma (1); Lung squamous cell carcinoma (1); lymphoid neoplasm (1); mesothelioma (1); ovarian carcinoma (1); ovarian serous cystadenocarcinoma (1); pancreatic adenocarcinoma (1); paraganglioma (1); pheochromocytoma (1); prostate adenocarcinoma (1); sarcoma (1); sinonasal carcinoma (1); soft tissue sarcoma (1).
A further 7 diseases each share a sentence with PHF5A in 1 paper.